TAL1 (TAL bHLH transcription factor 1, erythroid differentiation factor)
Diseases named in the same sentence as TAL1 in open-access papers (continued):
Sharing a sentence is not in itself a finding about the gene and the disease.
infection (6 papers, 2009 to 2025). The state of being infected such as from the introduction of a foreign agent such as serum, vaccine, antigenic substance or organism. "Lentiviral infection of KOPT-K1 cells expressing an LMO2 biodegrader showed collateral loss of TAL1 and E47 proteins with LMO2." (PMID 41385269, 2025). "Evidence from our study suggests that reductions in infection with age may be linked to changes in the balance of TAL1-IgE and TAL1-IgG4." (PMID 20856909, 2010). "The expression of most genes was not induced (with the exception of Tal1) during infection in WT mice in both organs, while they increased in infected Mif−/− mice." (PMID 25255103, 2014).
blood disorders (2 papers, 2016 to 2024). "A comprehensive understanding of the role of TAL1 in normal hematopoiesis and its dysregulation in leukemogenesis emphasizes its importance as a potential therapeutic target in blood disorders." (PMID 39349824, 2024).
cardiovascular disease (1 paper, 2022). "We constructed an mRNA–miRNA–lincRNA ceRNA interaction network centered on miR-22-3p and used the starBase v2.0 and miRWalk databases to predict eight related transcription factors associated with cardiovascular disease, namely, CTCF, JUN, JUND, NFATC1, NFE2L2, RAD21, RELA, and TAL1." (PMID 36105099, 2022).
hematological cancer (1 paper, 2022). "Analysis by LC-MS/MS identified more than 600 Lmo2-interacting molecules in physiological LPs, including the previously reported components of Lmo2 complexes in hematological cancer cell lines, Lyl1, Tal1, Ldb1, Tcf12, Tcf3, and Cbfa2t3 (also known as ETO2 or MTG16)." (PMID 36126774, 2022).
Renal Disease (1 paper, 2013). "The Hairpatches mouse model allows an investigation into the effects of Tal1, a transcription factor characterized by complex regulation patterns, and its effects on renal disease." (PMID 23301070, 2013).
TAL1 also shares sentences with these, for which no sentence is quoted: acute myeloid leukemia (3 papers); myeloid leukemia (3); colorectal cancer (2); hepatocellular carcinoma (2); influenza (2); acute promyelocytic leukemia (1); Bernard-Soulier Syndrome Type C (1); blood cancers (1); chronic myelomonocytic leukemia (1); clear cell renal cell carcinomas (1); coronary artery disease (1); depression (1); diffuse large B-cell lymphoma (1); Disseminated intravascular coagulation (1); Down syndrome (1); endothelial dysfunction (1); gastric cancer (1); ischemic disease (1); Macrothrombocytopenia (1); malignant mesothelioma (1); mantle cell lymphoma (1); myelodysplastic syndrome (1); myocardial infarction (1); osteoporosis (1); pancreatic neuroendocrine tumor (1); peripheral T cell lymphoma (1); prostate carcinoma (1); retinoblastoma (1); sarcoma (1); Spinal hemangioblastoma (1).
A further 5 diseases each share a sentence with TAL1 in 1 paper.